RNF43 (ring finger protein 43)
Diseases named in the same sentence as RNF43 in open-access papers (continued):
Sharing a sentence is not in itself a finding about the gene and the disease.
cancer (continued). "Conversely, overexpression of ZNRF3 and RNF43 suppresses cancer cell proliferation, migration and invasion, and drug resistance in multiple human cancer cell lines." (PMID 38260423, 2024). "Our study aims to clarify the functions of RNF43 in predicting the prognosis, immune signature, and immunotherapeutic efficacy in pan-cancer." (PMID 37848933, 2023). "By using RNA-seq, mutation, and clinical data from the TCGA database, the expression levels and prognostic significance of RNF43 in pan-cancer were analyzed." (PMID 37848933, 2023). "Firstly, we investigated RNF43 expression in normal tissues in the GTEx database and cancer cell lines in the CCLE database." (PMID 37848933, 2023). "The results demonstrated that RNF43 was abnormally expressed in multiple cancers, and RNF43 is a critical prognosis-related factor in several cancers." (PMID 37848933, 2023). "To explore the expression pattern of RNF43 in different cancers, we studied RNF43 expression in various cancers from the TCGA pan-cancer dataset." (PMID 37848933, 2023). "To further verify the predictive value of RNF43 for immunotherapeutic efficacy, we extracted three datasets enrolling cancer samples that achieved immunotherapies from the GEO database." (PMID 37848933, 2023). "In the present study, we performed systemic research on the promising roles of RNF43 in predicting the prognosis and immune phenotypes in human cancers." (PMID 37848933, 2023). "Gene Set Enrichment Analysis (GSEA) was performed to investigate the potential biological functions and signaling pathways modulated by RNF43 in cancers." (PMID 37848933, 2023). "In conclusion, the pan-cancer analysis comprehensively reveals that RNF43 can effectively predict the prognosis, immune-related phenotypes, and immunotherapy efficacy in human cancers." (PMID 37848933, 2023). "Next, the differential RNF43 expression between cancer samples and their compared normal samples in the TCGA pan-cancer dataset was further analyzed." (PMID 37848933, 2023). "Our research revealed that cancer patients with high RNF43 expression had better responses to anti-PD-1/PD-L1 treatment." (PMID 37848933, 2023). "Generally, the expression pattern and prognostic value of RNF43 were distinguished among different cancer types, and RNF43 can function as a critical prognosis-related factor in several cancers." (PMID 37848933, 2023). "Inactivating RNF43 or ZNRF3 mutations result in increased Wnt receptor levels in mammalian cells and promote the growth of numerous human cancers, including colorectal, endometrial, ovarian, pancreatic, gastric, and adrenocortical carcinomas." (PMID 37798281, 2023). "Our study found that RNF43 expression was negatively related to Th1 in UVM and Th2 in COAD, indicating the potential functions of RNF43 in regulating Th1/2 cells in these cancers." (PMID 37848933, 2023). "Truncating mutation, amplification, and missense mutation were the main types of frequent genetic alterations of RNF43 in pan-cancer." (PMID 37848933, 2023). "To identify Food and Drug Administration (FDA)-approved drugs that selectively target cancer cells with inactivated RNF43 and PWWP2B genes, we performed a high-throughput screening of 1,449 drugs in HAP1, HAP1 RNF43 KO, and HAP1 PWWP2B KO cells." (PMID 34149925, 2021).
cancer (continued). "Loss-of-function mutation of RNF43 and ZNRF3 leads to the hyper-responsiveness of Wnt signals and deregulations of R-spondin/ZNRF3/RNF43 feedback loops which is marked by various forms of cancers." (PMID 34535145, 2021). "By comparing the transcriptome sequences of the cancer tissues with their matched normal tissues, we identified differentially expressed genes, including RNF43 and PWWP2B." (PMID 34149925, 2021). "Mutations introducing premature termination codons (PTC) within this RNF43 region occurred in various cancer types, including pancreas, endometrium, ovarium, and colon." (PMID 32965059, 2020). "In keeping with previous studies (p43), RNF43 was identified as a putative cancer driver (p = 0.07)." (PMID 32384699, 2020). "In pancreatic ductal adenocarcinoma, loss-of-function mutations of RNF43 and ZNRF3 correlated with cancer development while amplification of R-spondin genes was reported in more than 18% samples of patients affected by colorectal and endometrial cancer." (PMID 32046053, 2020). "RNF43 and its homolog ZNRF3 are transmembrane E3 ubiquitin ligases frequently mutated in many human cancer types." (PMID 32527265, 2020). "To further investigate the role of RNF43 in tumorigenesis, we identified patient mutations downstream of the RING-finger domain using the COSMIC database for mutations in cancer." (PMID 32934222, 2020). "For example, RNF43 and RPSO3 mutations cause increased abundance of Wnt receptors on the cell surface, making the cancer cells addicted to Wnt signaling." (PMID 33092630, 2020). "To assess the activity of the FZD5-specific FLAg, we used RNF43 mutant cancer cells in which Wnt-βcatenin signaling mediated through FZD5 is essential for proliferation." (PMID 31452509, 2019). "The co‐occurred mutations in RNF43 and FAT3/FAT4 disrupted the Wnt signaling and thus promoted the development of cancer." (PMID 30107644, 2018). "We detected a trend for decreased RNF43 expression in cancer tissues compared with the corresponding normal tissues (P < 0.01)." (PMID 28446252, 2017). "A lack of association of other E3 ubiquitin ligases and stemness indicated a unique function of RNF43 in stem-like cancer cells." (PMID 28446252, 2017). "Ring finger protein 43 (RNF43) is an E3 ubiquitin ligase originally found in stem cells and is mutated in several kinds of carcinomas." (PMID 28446252, 2017). "Discovery of the R-spondin-ZNRF3/RNF43 signaling module and its genetic alterations in cancers represents a breakthrough in this area." (PMID 27338477, 2016). "RNF43 transcript expression was lower in RNF43 mutant compared to RNF43 wild type cancers (mean of 6.91 and 8.49 respectively; p=0.0002)." (PMID 27661107, 2016). "Recent studies suggest that the R-spondin-ZNRF3/RNF43 signaling module is frequently disrupted in cancer." (PMID 27338477, 2016). "This was observed in the majority of BRAF wildtype cancers where elevated cytoplasmic RNF43 staining was also observed, likely as a futile attempt to dampen the Wnt signal by RNF43-mediated degradation of the Frizzled receptor." (PMID 27661107, 2016). "Cancers with an X659fs mutation had lower expression compared to cancers harbouring other mutations (average of 6.5 and 8.15 respectively; p=0.01) and compared to RNF43 wild type cancers (p<0.0001)." (PMID 27661107, 2016). "In BRAF mutant/MSI cancers with normal staining for β-catenin, 21/33 (63.6%) also maintained normal RNF43 staining compared to only 4/23 (17.4%) BRAF mutant/MSS cancers (P<0.001)." (PMID 27661107, 2016). "RNF43 was mutated in 47/54(87%) BRAF mutant/MSI and 8/33(24%) BRAF mutant/microsatellite stable cancers compared to only 3/79(4%) BRAF wildtype cancers (p<0.0001)." (PMID 27661107, 2016). "The presence of RNF43 mutations was examined in 54 BRAF mutant/MSI, 33 BRAF mutant/MSS and 79 BRAF wild type cancers." (PMID 27661107, 2016). "Mouse genetic studies have supported a critical role of the R-spondin-ZNRF3/RNF43 signaling module in cancer." (PMID 27338477, 2016).
cancer (continued). "Overall this study has identified that the E3 ubiquitin ligases, RNF43 and ZNRF3, are frequently mutated in BRAF mutant cancers of the serrated pathway, particularly those that are MSI." (PMID 27661107, 2016). "Although the counterpart has not been studied comprehensively in the mammalian system, the mutations of RNF43, ZNRF3 and RSPO2/3 in cancer supports the importance of this mechanism to fine-tune cell responsiveness to Wnt." (PMID 25208913, 2014). "The RSPO/LGR5/RNF43/Frizzled pathway is critical in both normal stem cell maintenance and in cancer." (PMID 25208913, 2014). "The higher-than-normal tissue expression of COL3A1, DLG3, and RNF43 in some of the cancer tissues is in agreement with our in silico predictions." (PMID 23282184, 2012). "In summary, our study introduces a novel concept in Wnt signaling regulation at the FZD receptor level, clarifies the mechanisms by which RSPO-ZNRF3/RNF43 regulates Wnt signaling, and offers new insights into Wnt signaling-related regenerative medicine and cancer therapy." (PMID 39463927, 2025). "Our results reveal a novel negative regulatory mechanism of Wnt signaling at the receptor level and illuminate the mechanism by which RSPO-ZNRF3/RNF43 regulates Wnt signaling, which may provide new insights into regenerative medicine and cancer therapy." (PMID 39463927, 2025). "Consequently, our data point to druggable vulnerabilities of specific FZD receptors in RNF43- or ZNRF3-mutant human cancers." (PMID 38969364, 2024). "Our results suggest that the rationale for integration of RNF43 in broader cancer gene panels can be questioned– and that the genetic counseling of the family should be handled carefully, considering cancer and SPS family history and with information about reservations." (PMID 39546056, 2024). "However, our proteogenomic studies have revealed EGFR as the protein most negatively correlated with ZNRF3/RNF43 mRNA levels in multiple human cancers." (PMID 38260423, 2024). "Importantly, in cancer patients, ZNRF3 and RNF43 are frequently inactivated by gene deletion or loss-of-function mutations." (PMID 38260423, 2024). "Collectively, these results suggest that disruption of ZNRF3 and RNF43 may up-regulate EGFR protein levels in human cancers." (PMID 38260423, 2024). "Additionally, we substantiated our findings in multiple cell lines, human cancer cell xenograft models, and genetically engineered mouse models, wherein the loss of ZNRF3/RNF43 resulted in elevated EGFR levels and facilitated cancer progression." (PMID 38260423, 2024). "However, in cancer cells, alterations such as recurrent RSPO gene fusion or ZNRF3/RNF43 deletion or mutations disrupts this feedback loop, resulting in hyperactive WNT signaling and subsequent cancer development and progression." (PMID 38260423, 2024). "Interestingly, these observations correlate with the differential prevalence of RNF43 and ZNRF3 mutations in human cancer subtypes originating from specific tissues." (PMID 38969364, 2024). "Furthermore, since EGFR is mutationally activated in some human cancers, we transfected a common mutant – EGFR L858R – into RNF43 WT vs. KO HT29 cells and compared the resulting protein levels." (PMID 38260423, 2024). "Further work should explore the extent to which EGFR and WNT receptors (Frizzled and LRP5/6) each transmit the effect of ZNRF3/RNF43 deactivation at different cancer stages and investigate the efficacy of blocking both EGFR and WNT signaling in treatment of ZNRF3/RNF43-deactivated tumors." (PMID 38260423, 2024). "In addition, by examining tissue-specific expression patterns we translate FZD-specific roles to the incidence of RNF43 and ZNRF3 mutations in cancer." (PMID 38969364, 2024).
cancer (continued). "Further research on ZNRF3/RNF43 regulation of EGFR versus WNT receptors in different cancer stages can contribute to a comprehensive understanding of RSPO-ZNRF3/RNF43 signaling in cancer progression and provide valuable knowledge for potential therapeutic interventions." (PMID 38260423, 2024). "For that reason these RNF43-mutant cancers have gained substantial therapeutic interest, as they may identify tumors that respond to extracellular Wnt-inhibitors that have been developed, such as FZD antibodies and Wnt-secretion Porcupine inhibitors." (PMID 37023034, 2023). "RNF43 and LRP1B were among the genes, most commonly mutated in GC, lending support to the hypothesis that these genes are important for cancer development and/or progression." (PMID 36823311, 2023). "Besides, drug metabolism cytochrome P450 and neuroactive ligand-receptor interaction were also critical signaling pathways modulated by RNF43 in pan-cancer." (PMID 37848933, 2023). "The RNF43 was differently expressed in diverse normal tissues and cancer cell lines." (PMID 37848933, 2023). "Besides, we discovered that cancer patients with RNF43-altered had a prolonged PFS time (p = 0.0133) and DSS time (p = 0.0441)." (PMID 37848933, 2023). "It was shown that RNF43 expression was significantly associated with various types of infiltrating immune-associated cells including dendritic cells, CD4+ T cells, CD8+ T cells, plasma cells, macrophages, B cells, and so on in diverse cancers." (PMID 37848933, 2023). "Besides, large-scale cohorts are urgently warranted to explore the predictive value of RNF43 in pan-cancer outcomes and immunotherapy efficacy, which is time-consuming." (PMID 37848933, 2023). "Besides, olfactory transduction, drug metabolism cytochrome P450, and neuroactive ligand receptor interaction were identified as the most three common signaling pathways in RNF43 biological function in pan-cancer analysis." (PMID 37848933, 2023). "The results of the GSEA analysis showed that RNF43 was obviously involved in detection of chemical stimulus, detection of stimulus involved in sensory perception, and sensory perception of chemical stimulus in pan-cancer." (PMID 37848933, 2023). "Finally, IHC explored and validated the different expression levels of RNF43 in different cancers by our clinical samples." (PMID 37848933, 2023). "To assess the predictive and prognostic value of RNF43 in pan-cancer, we conducted Cox regression analysis and Kaplan–Meier survival analysis to evaluate the relationship between RNF43 expression and cancer patients’ survival outcomes, including OS, DFS, DSS, and PFS." (PMID 37848933, 2023). "We first investigated the expression-based panoramic picture of RNF43 in different cancer types." (PMID 37848933, 2023). "The average alteration frequency of RNF43 in pan-cancer was high as 4%." (PMID 37848933, 2023). "Thus, both, RNF43 and LRP1B are among the most commonly mutated genes in GC underscoring their putative significance in cancer development and progression." (PMID 36823311, 2023). "It is important to note that whilst there have been promising results treating RNF43 or RSPO2/3 mutant cancers with porcupine inhibitors, one on-target side effect of these drugs is a loss of bone density since WNT signalling plays an important role in bone homeostasis." (PMID 37048063, 2023). "In addition, KEGG analysis revealed that olfactory transduction was the most common signaling pathway of RNF43 participating in multiple cancer types." (PMID 37848933, 2023). "The other genes, which are not included in the nine major cancer signaling pathways, are sporadically mutated, although those in the RNF43 sequence occur more frequently." (PMID 37509254, 2023). "Interestingly, we detected a mutation in RING-type E3 ubiquitin ligase (RNF43), a gene which is reported to negatively regulate WNT signaling in cancer present in clonal clusters across all cases and timepoints." (PMID 37758711, 2023).
cancer (continued). "By employing the CellMineTM database, we found that RNF43 expression was significantly correlated with the sensitivity of several drugs that have been widely applied in cancer clinical treatment or clinical trials, such as cisplatin, erlotinib, cobimetinib, and everolimus." (PMID 37848933, 2023). "Furthermore, Kaplan–Meier cumulative curves showed that RNF43 expression levels were related to OS in 3 cancers, DFS in 5 cancers, DSS in 4 cancers, and PFS in 5 cancers." (PMID 37848933, 2023). "To probe into the effects of miR-181d-5p/RNF43/Wnt signaling pathway axis on cancer stemness and RCC progression in vivo, we firstly constructed miR-181d-5p stably overexpressed or blocked ACHN cells with miR-181d-5p overexpression lentivirus or sponge lentivirus, respectively." (PMID 36319622, 2022). "Similarly, mutations of RNF43 and RNF43/ZNRF3 or RSPOs also play a pivotal role in the activation of oncogenic pathways in various cancers and determine the cancer onset." (PMID 36139498, 2022). "RNF43, an E3 ubiquitin-protein ligase that acts as a negative regulator of the Wnt signaling pathway, is reported to be associated with various cancer types including PAAD." (PMID 35336734, 2022). "Importantly, based on our preclinical finding, docetaxel trihydrate, pelitinib, and uprosertib have significant anti-cancer effects in cancers with low RNF43 and PWWP2B expression (HAP1 RNF43 KO, HAP1 PWWP2B KO cells, MKN45 cells, and KMN45 xenografts)." (PMID 34149925, 2021). "Many RNF43 cancer-associated mutations occur outside the N-terminal extracellular and cytoplasmic RING-finger domains, which regulate Fzd binding and ubiquitination, respectively, suggesting additional levels of RNF43 regulation." (PMID 32934222, 2020). "Importantly, our findings predict differential sensitivity of these RNF43 mutational classes to treatment with PORCN inhibitors, Wnt antagonists that are currently evaluated for clinical treatment of RNF43‐mutant cancer patients." (PMID 32965059, 2020). "Transmembrane RING-type ubiquitin ligase RNF43 inhibits the non-canonical pathway in a ubiquitination-independent manner, and cancer-associated mutations of RNF43 do not have any effect on this activity." (PMID 31623112, 2019). "In cancer cells, the mutant RNF43 would co-express with WT RNF43, and could possibly inhibit the function of the WT enzymes if WT and mutant enzymes could form inactive dimers." (PMID 31811196, 2019). "Moreover, the inhibitor IWP-2 is proposed for the treatment of cancer, especially CRC due to RNF43 mutations, whereas PORCN inhibitors WNT974 and ETC-159 are applicable to cancer stem cells." (PMID 31684152, 2019). "The duration rather than age was relevant because somatic mutations of RNF43 did not associate with neither age at IBD onset nor age at cancer diagnosis." (PMID 29416670, 2018). "Diagnostically, RNF43 mutations occur in early-stage gastric lesions, which could be used to stratify patients who may benefit from compounds that block the secretion of Wnt ligands, which have substantial efficacy in other ‘Wnt-addicted’ RNF43 mutant cancers." (PMID 29570681, 2018). "Furthermore, we also detected RNF43 expression in other cancer types and their adjacent normal tissues using the same IHC staining method." (PMID 28446252, 2017). "SETD2, PTEN, RNF43, HRAS, EPHA2, and BAP1 were also linked to primarily positive associations in more than one cancer type, suggesting that they may play a general role in CGI hypermethylation." (PMID 29125844, 2017). "The impact of RNF43 on cancer cells varies with cancer types." (PMID 28446252, 2017). "Second, surface marker analysis demonstrated that the stem-like cancer cells only account for a small population of the total cells, which might result in an inaccuracy of the effect of RNF43 on CSCs." (PMID 28446252, 2017).